DYRK2 (dual specificity tyrosine phosphorylation regulated kinase 2)
Diseases named in the same sentence as DYRK2 in open-access papers (continued):
Sharing a sentence is not in itself a finding about the gene and the disease.
Parkinson disease (1 paper, 2022). A progressive degenerative disorder of the central nervous system characterized by loss of dopamine producing neurons in the substantia nigra and the presence of Lewy bodies in the substantia nigra and locus coeruleus. "Knocking down DYRK2 promotes oligomerization of alpha-synuclein suggesting a protective role for DYRK2 in Parkinson’s Disease since oligomers are considered toxic." (PMID 36161154, 2022).
psoriasis (1 paper, 2025). An autoimmune condition characterized by red, well-delineated plaques with silvery scales that are usually on the extensor surfaces and scalp. "Among psoriasis proteins, NF-Kappa-B1 (PDB ID: 8TQD), Interleukin 12 receptor subunit beta−1 (PDB ID: 6WDP) and DYRK2 (PDB ID: 6HDR) exhibit highly negative binding energies, indicating strong and possibly irreversible ligand interactions." (PMID 40572592, 2025).
respiratory failure (1 paper, 2021). The significant impairment of gas exchange within the lungs resulting in hypoxia, hypercarbia, or both, to the extent that organ tissue perfusion is severely compromised. "We find that Dyrk2-deficient mice exhibit congenital malformations of multiple organs and death soon after birth due to respiratory failure." (PMID 34671097, 2021). "We further examined the details of lung development in Dyrk2−/− mice to determine the causal phenotype of lung hypoplasia and respiratory failure." (PMID 34671097, 2021). "We found that Dyrk2−/− mice died due to respiratory failure." (PMID 34671097, 2021).
uterine corpus endometrial carcinoma (1 paper, 2022). A endometrial carcinoma (disease) that involves the body of uterus. "The highest frequency of alterations in DYRK2 (~ 5% frequency) was seen in patients with Uterine Corpus Endometrial Carcinoma, with 'mutations' being the predominant type." (PMID 36104345, 2022).
tumor (42 papers, 2010 to 2026). "We found a statistically positive correlation between DYRK2 expression and tumor-associated fibroblast infiltration values in BLCA, BRCA-LumA, HNSC [HPV (Human papillomavirus) + / −],LUSC,OV,PAAD,SARC and SKCM." (PMID 36104345, 2022). "In the tumour microenvironment, the expression of DYRK2 correlates with cancer-associated fibroblast infiltration, such as BLCA or HNSC." (PMID 36104345, 2022). "In animal studies, the overexpression of DYRK2 was associated with impaired tumor growth, in addition to inhibiting Twist and Vimentin expression while enhancing Vimentin expression within CRC xenograft tumors." (PMID 36577753, 2022). "More advanced tumor differentiation was additionally associated with DYRK2 downregulation in these CRC tissue samples." (PMID 36577753, 2022). "DYRK2 is a class II DYRK that has been more intensely studied in terms of its involvement in the events associated with tumor progression." (PMID 32751160, 2020). "The analyzed point mutations were selected based on their presence in tumor tissues, the calculated damage probability score and their frequency of observation in the Dyrk2 kinase." (PMID 32678104, 2020). "Second, Dyrk2 possibly contributes to cancer progression; it has been implicated as both a putative tumor suppressor and an oncogene." (PMID 32678104, 2020). "Thus, DYRK2 is a key regulator of DNA damage response pathways and stress signals, and it has been implicated in several human cancers with both oncogenic and tumor suppressor activities." (PMID 36934104, 2023). "Indeed, protein levels of DYRK2 positively correlate with active HSF1 levels in TNBC patient tumours and together associates with poor outcome." (PMID 36622366, 2023). "Furthermore, DYRK2-associated molecular functions have been linked to tumor cells such as G1/S transition, epithelial-mesenchymal-transition, and stemness of cancer cells." (PMID 34363019, 2022). "In summary, the first pan-cancer analysis of DYRK2 showed a statistical correlation between DYRK2 expression and clinical prognosis, DNA methylation, protein phosphorylation of clinical tumor samples, immune cell infiltration, and tumour mutation burden." (PMID 36104345, 2022). "Contrary to this, various medicinal chemistry studies reported robust antiproliferative properties of DYRK2 inhibitors, whereas unbiased ‘omics’ and genome-wide association study-based studies identified DYRK2 as a highly overexpressed kinase in various patient tumor samples." (PMID 33376136, 2021). "For malignancies in which DYRK2 expression is associated with tumor progression, the use of DYRK2 inhibitors may be an alternative therapeutic approach." (PMID 33067577, 2020). "A few works have explored the mechanisms underlying the reduction of DYRK2 levels in tumor cells." (PMID 32751160, 2020). "In addition, overexpression of Dyrk2 was found to be associated with tumor progression in gastrointestinal stromal tumors." (PMID 24676346, 2014). "Similarly, the analysis of the frequency of loss-of-function mutations on DYRK2 and/or NOTCH1 in tumours showed that mutations on DYRK2 and NOTCH1 occur very rarely together, suggesting that both proteins might be in the same pathway." (PMID 31605148, 2020). "During the past 10 years, DYRK2 has been identified as a tumour suppressor in a range of malignancies, initiating significant antitumor and proapoptotic responses." (PMID 39731274, 2025). "DYRK2 overexpression using an adenovirus vector also suppressed tumor size and weight, significantly reduced the proportion of Ki-67, a cell proliferation marker, and increased cleaved caspase 3, an apoptosis induction marker." (PMID 37886981, 2023).
tumor (continued). "Tissues from patients with different cancers were studied to evaluate the role of DYRK2 as a tumor suppressor and oncogene." (PMID 37886981, 2023). "Since tumours derived from H-KO cells grew much more slowly than those from parental cells, it was difficult to unambiguously conclude the effect of a further DYRK2 depletion on tumour growth in H-KO cells." (PMID 36622366, 2023). "These experiments illustrate the importance of both DYRK2 and HSF1 for TNBC tumour growth and further show that DYRK2 plays a major role in the growth of HSF1-proficient tumours." (PMID 36622366, 2023). "Furthermore, cancer cell lines and patient tumor tissues are cancerous; therefore, it is difficult to determine whether tumorigenesis and/or tumor development cause changes in DYRK2 expression or whether changes in DYRK2 expression cause tumorigenesis and/or tumor development." (PMID 37886981, 2023). "In cell lines, KLF4 expression inversely correlated with DYRK2 expression and induced tumor formation in a xenograft mouse model." (PMID 37886981, 2023). "We used UALCAN to analyze the difference of DYRK2 promoter methylation level between tumor and adjacent normal tissues." (PMID 36104345, 2022). "Immunohistochemistry of DYRK2 in these patient-derived PCa tumors also demonstrated that the expression of DYRK2 in tumor tissues was much higher than in normal tissues." (PMID 35614066, 2022). "Together, these data confirmed that DYRK2 can regulate tumor growth and EMT induction in part via suppressing Twist expression." (PMID 36577753, 2022). "This better illustrates that DYRK2 is involved in tumorigenesis and development and plays an important role in the tumor microenvironment." (PMID 36104345, 2022). "Through analyses of TMAs and the TCGA database, DYRK2 was found to be downregulated in CRC tumor tissues relative to healthy colorectal tissue samples, with its downregulation being associated with patient clinicopathological characteristics." (PMID 36577753, 2022). "While AKT1, mTORC1, MEK1, p38 and DYRK2 can all activate HSF1, the current study indicates that activity of only AKT1 and mTORC1 maintains a strong association with HSF1 activity in tumours." (PMID 35080342, 2022). "Next, animal model experiments were conducted revealing that the overexpression of DYRK2 significantly reduced tumor growth with respect to both tumor volume and tumor weight." (PMID 36577753, 2022). "Initial analyses of the Tumor Immune Estimation Resource (TIMER) database analysis were used to explore the expression of DYRK2 at the mRNA level in a range of cancers." (PMID 36577753, 2022). "In vivo studies further confirmed that the overexpression of DYRK2 inhibited human CRC xenograft tumor growth with concomitant Twist downregulation." (PMID 36577753, 2022). "The expression level of DYRK2 widely depends on the human tumor tissues, and it plays diverse roles in the occurrence and development of various cancers, which highlights the possibility of DYRK2 as a potential target for cancer treatment." (PMID 35614066, 2022). "H&E staining and Ki-67 immunohistochemical analysis of tumor tissues indicated that knock-down of DYRK2 exhibited potent efficacy of killing tumor cells and inhibiting PCa cell proliferation." (PMID 35614066, 2022). "Alterations in DYRK2 expression have been found in multiple human tumor tissues, both with higher and lower levels than in healthy tissue." (PMID 34363019, 2022). "In this study, the role of DYRK2 as a mediator of CRC cell drug resistance and the associated molecular mechanisms were assessed by evaluating human tumor tissue samples, CRC cell lines, and animal model systems." (PMID 36577753, 2022). "In agreement, the analysis of the expression levels of CDC25A and DYRK2 in different cancer types with available normal-tumor matched data identified the opposite behavior of both genes." (PMID 34363019, 2022).
tumor (continued). "In summary, the down-regulation of DYRK2 remarkably reduced PCa tumor burden in vitro and in vivo, suggesting that DYRK2 played a critical function in regulating PCa and is a potential therapeutic target for the treatment of PCa." (PMID 35614066, 2022). "This helps to understand the role of DYRK2 in tumorigenesis from the perspective of clinical tumor samples, and points out a new direction for cancer clinical treatment." (PMID 36104345, 2022). "With multiple kinases including PKCδ, HIPK2, ataxia-telangiectasia mutated kinase, and p38α phosphorylating Ser46 upon genotoxic stress, it is hard to decipher to what extent DYRK2 contributes to this tumor suppressor role." (PMID 33376136, 2021). "Dual phosphorylation of c-Myc on Thr58 and Ser62 triggers binding to an E3 ubiquitin ligase SCF-Fbxw7 (Skp-Cullen-F-box) and consequent proteasomal degradation of c-Myc, thus leading to the proposed tumor suppressor role of DYRK2." (PMID 33376136, 2021). "Both the studies used a DYRK2 overexpression system to show that higher DYRK2 decreased tumor formation." (PMID 33376136, 2021). "By interrogating publicly available datasets, we show that, as recently reported, DYRK2 mRNA levels are often higher in tumour than in normal tissue, correlating in some cases with poor patient survival." (PMID 33268814, 2021). "This is in sharp contrast to others reporting DYRK2 depletion reduces proliferation and tumor formation potential of MDA-MB-231 cells." (PMID 33376136, 2021). "In 2003, the chromosome 12 region 12q13-14 was found to be amplified in adenocarcinomas of the lung and esophagus, and one of the resident genes, DYRK2, was significantly overexpressed in tumor samples as compared with normal tissues." (PMID 33376136, 2021). "We further show that in clinical TNBC samples DYRK2 protein levels correlate with active HSF1, and are associated with high rates of tumour recurrence and poorer patient survival." (PMID 33268814, 2021). "Among the genes negatively regulated by KDM4B, STARD7, CPA4, FKBP14, and RNF6 have been shown to regulate cell proliferation and/or metastasis, whereas DYRK2 is a known tumor suppressor." (PMID 34766154, 2021). "Studies have reported that DYRK2 can inhibit tumor cell proliferation via interactions with a variety of tumor suppressor genes, and reduced DYRK2 expression is strongly linked to weak chemotherapeutic efficacy and poor prognosis." (PMID 34766149, 2021). "We have recently showed that DYRK2 protein levels are higher in TNBC tumours than in adjacent normal tissue, however, the relationship between DYRK2 protein levels and patient survival in different tumour types has not been properly studied." (PMID 33268814, 2021). "Based on results from xenograft experiments using MCF-7 cells, a tumor-suppressor role was first proposed given that DYRK2 silencing favored tumor growth." (PMID 32751160, 2020). "Tumor growth was potentiated after DYRK2 silencing in xenograft models, thereby revealing the clear implications of this event in cancer development." (PMID 32462403, 2020). "Expression of Akt, PI3K and MDR1 in tumor tissue exposed to a circadian-rhythm disorder was higher (DYRK2 expression was lower) than that of tumor tissue exposed to a normal circadian rhythm." (PMID 33083827, 2020). "Further supporting a tumor-suppressive function for DYRK2 and the potential of DYRK2 stabilization as an anticancer therapy, ectopic expression of DYRK2 inhibits cell proliferation, induces cell death, and prevents tumor growth in liver cancer." (PMID 33067577, 2020). "Expression of Akt, PI3K and MDR1 in tumor tissue exposed to a circadian-rhythm disorder was higher than that in tumor tissue exposed to a normal circadian rhythm (DYRK2 expression was lower), and the difference was statistically significant (P<0.01)." (PMID 33083827, 2020).
tumor (continued). "Several clues have been obtained regarding the putative molecular mechanisms responsible for DYRK2-mediated tumor development/progression." (PMID 32751160, 2020). "The biochemistry and biology of DYRK2 was covered in recent reviews, and thus, here, we will center on the activity of this kinase in the context of tumor biology." (PMID 32751160, 2020). "In the same way, the bibliography includes many works which analyze DYRK2 expression in human tumor tissue compared to adjacent healthy tissue at different levels." (PMID 32462403, 2020). "Our analysis of TCGA data found DYRK2 to be overexpressed in eight tumor cohorts: bladder (BLCA), breast (BRCA), esophagus (ESCA), kidney (KIRC and KIRP), liver (LIHC), lung (LUAD and LUSC) and stomach (STAD)." (PMID 32751160, 2020). "DYRK2 can also regulate cancer invasion and metastasis by degrading Snail; therefore, shRNA silencing of DYRK2 promoted tumor invasion and metastasis in immunodeficient mice subcutaneously implanted with MCF-7 cells." (PMID 33067577, 2020). "Expression of Akt, PI3K, MDR1 and MRP1 in the tumor tissues of the drug-resistant group was higher than that in the tumor tissues of the cisplatin-sensitive group (DYRK2 expression was lower), which are the proteins related to drug resistance." (PMID 33083827, 2020). "Although DYRK2 distinct role in cancer development has been broadly proved, there is controversy concerning its pro- or anti-tumour potentials." (PMID 31605148, 2020). "Lower protein levels of DYRK2 significantly correlated with tumor location in rectum, advanced tumor stage and unfavorable prognosis in clinical stage III and IV CRC patients." (PMID 27532268, 2016). "Our study offers the first piece of evidence that shows the significant correlation between lower protein level of DYRK2 and tumor location in rectum, advanced tumor stage and unfavorable prognosis in clinical stage III and IV CRC patients." (PMID 27532268, 2016). "Studies of Taira et. al suggested that DYRK2 regulated tumor progression in vivo an in vitro through the modulation of c-Jun and c-Myc." (PMID 27532268, 2016). "Similarly, low DYRK2 expression has generally been reported in human tumor tissues and correlated with reduced survival, invasiveness, or poor prognosis." (PMID 36934104, 2023). "In addition, DYRK2 knockout MDA-MB-231 cells showed a reduced tumor burden in xenograft mouse models, which was recovered through DYRK2 reintroduction." (PMID 37886981, 2023). "Indeed, tumour volume and tumour weight were significantly lower in the H-KO cells bearing shRNA-targeting DYRK2 compared with scrambled control." (PMID 36622366, 2023). "Taken together, DYRK2, as a tumor suppressor, may inhibit metastasis by inducing E-cadherin expression, suppressing S100A4, EMA, and N-cadherin expression, and promoting autophagy by increasing Beclin1 and LC3 expression." (PMID 37886981, 2023). "However, the roles of DYRK2 as both a tumor suppressor and oncogene have been reported in some cancers." (PMID 37886981, 2023). "Taken together, DYRK2 as a tumor suppressor may regulate cell stemness and tumor formation through an inhibitory interaction with KLF4." (PMID 37886981, 2023). "Similarly, DYRK2 knock-down cell-derived tumours were smaller in volume and weight than parental as well, which is consistent with our own previous work." (PMID 36622366, 2023). "Interestingly, tumours derived from H-KO cells bearing shRNAs against DYRK2, exhibited a statistically significant reduction in tumour weight compared with all scrambled control cells (parental and H-KO)." (PMID 36622366, 2023). "In a xenograft study, tumor growth rate, volume, and weight were inhibited by DYRK2 overexpression." (PMID 37886981, 2023). "Nevertheless, this new mechanism might have important implications for tumor development control, and points at DYRK2 as a potential target to explain the increased tumorigenesis and chemotherapy resistance caused by alterations in FBXW7." (PMID 36934104, 2023).